NPM1P3 (nucleophosmin 1 pseudogene 3)
Synonyms: NG3-3; formerly NPMP3; NPM1P15
Gene: Processed pseudogene on chromosome 16 (5,365,797 to 5,366,688, forward strand). Ensembl gene ENSG00000261007.
Diseases named in the same sentence as NPM1P3 in open-access papers:
NPM1P3 is named in the same sentence as 2 diseases in open-access papers, as found by Europe PMC text mining. Sharing a sentence is not in itself a finding about the gene and the disease.
NPM1P3 shares sentences with these, for which no sentence is quoted: cancer (1 paper); psychiatric disorder (1).